ALDH1A1 (aldehyde dehydrogenase 1 family member A1)
Diseases named in the same sentence as ALDH1A1 in open-access papers (continued):
Sharing a sentence is not in itself a finding about the gene and the disease.
rectal cancer (10 papers, 2015 to 2026). A primary or metastatic malignant neoplasm that affects the rectum. "Thus, ALDH1A1 is not a prognostic or predictive marker in colon or rectal cancers." (PMID 26783961, 2016).
esophageal squamous cell carcinoma (9 papers, 2013 to 2024). Esophageal squamous cell carcinoma (ESCC) is a type of esophageal carcinoma (EC) that can affect any part of the esophagus, but is usually located in the upper or middle third. "Additionally, ALDH1A1-high esophageal squamous cell carcinoma cells possess CSC properties and the expression of ALDH1A1 is associated with esophageal squamous dysplasia and carcinoma." (PMID 26783961, 2016). "Thus, ALDH1A1-positive cells were preferentially distributed in the invasion frontier of esophageal squamous cell carcinomas and metastatic lesions." (PMID 26783961, 2016). "Taken together, ALDH1A1-expressing cells are crucial for the development and progression of esophageal squamous cell carcinomas and ALDH1A1 may be used as a predictor of patient prognosis and a biomarker for malignancy of esophageal squamous cell carcinomas." (PMID 26783961, 2016). "Small molecule inhibitor NCT-501 down-regulated ALDH1A1 expression and inhibited AKT-β-catenin signaling pathway, and the proliferation of esophageal squamous cell carcinoma cells." (PMID 36484016, 2022).
myeloma (9 papers, 2012 to 2022). "Very similar ABCB1 regulation by ALDH1A1-NEK-2 axis was also observed in multiple myeloma, suggesting the significance of high ALDH1A1 regulating ABC transporters’ expression." (PMID 35328460, 2022). "Our studies showed that expression of ALDH1A1, the predominant isoform of ALDH1 in myeloma cells, leads to up-regulation of 9-cis retinoic acid (9CRA)." (PMID 26415231, 2015). "The finding suggested that ALDH1A1 enhanced the drug export activity of myeloma cells in an ABCB1-dependent manner." (PMID 25230277, 2014). "Over expression of ALDH1A1 in myeloma cells led to increased mRNA and protein levels of NIMA-related kinase 2 (NEK2), whereas shRNA-mediated knock down of NEK2 decreased drug efflux pump activity and drug resistance." (PMID 25230277, 2014). "Next we performed soft-agar colony formation assays to assess the possibility that ALDH1A1 promotes drug resistance in myeloma." (PMID 25230277, 2014). "Taken together, our results support the notion that ALDH1A1 is a promoter of drug resistance in myeloma that is worthy of consideration for therapeutic targeting in order to overcome MDR and improve the outcome of patients with myeloma." (PMID 25230277, 2014). "The results presented in panels C and D lent further support to the contention that ALDH1A1 renders myeloma cell drug resistance." (PMID 25230277, 2014). "Considering that NEK2 activates AKT and ABCB1 in myeloma, it is possible that ALDH1A1 promotes drug resistance by activating the NEK2-AKT pathway." (PMID 25230277, 2014). "The activation of NEK2 in myeloma cells relied on the ALDH1A1-dependent generation of the retinoid X receptor α (RXRα) ligand, 9-cis retinoic acid (9CRA) – not the retinoic acid receptor α (RARα) ligand, all-trans retinoic acid (ATRA)." (PMID 25230277, 2014). "We also demonstrate that over-expression of ALDH1A1 in myeloma leads to elevated NEK2 levels, using a mechanism that includes 9-cis retinoic acid-dependent RXRα signaling." (PMID 25230277, 2014). "We will briefly discuss the emerging role of ALDH1A1 in multiple myeloma, the regulation of reproduction, and immune responses, and conclude by discussing the role of ALDH1A1 in future therapeutic applications." (PMID 24594504, 2014). "Enforced expression of ALDH1A1 in myeloma cells led to increased activity of the drug efflux pump, ABCB1, and to more vigorous tumor growth in mice." (PMID 25230277, 2014). "Enforced expression of ALDH1A1 in myeloma cells led to increased clonogenicity, tumor formation in mice, and resistance to myeloma drugs in vitro and in vivo." (PMID 25230277, 2014). "In conclusion, this study implicates ALDH1A1 as an important drug resistance and tumor progression gene in multiple myeloma." (PMID 25230277, 2014). "Next, we employed the eFluxx-IDTM multidrug resistance assay to evaluate the possibility that up-regulation of ALDH1A1 leads to increased drug efflux activity in myeloma." (PMID 25230277, 2014). "Small-drug inhibitors that specifically target ALDH1A1 may be considered for therapeutic regimens aimed at overcoming drug resistance in myeloma." (PMID 25230277, 2014). "To elucidate the mechanism by which ALDH1A1 activates NEK2 in myeloma, we interrogated the chromatin immunoprecipitation sequencing (ChIP-Seq) database from the University of California Santa Cruz (UCSC) for chromatin occupancy patterns at the NEK2 promoter and NEK2 coding region." (PMID 25230277, 2014). "The apparent association of high ALDH1A1 and NEK2 levels is consistent with the hypothesis that NEK2 contributes to ALDH1A1-dependent drug resistance in myeloma." (PMID 25230277, 2014). "Next, we sought to determine whether ALDH1A1 is also the chief representative of the ALDH1 family in two human myeloma cell lines (HMCLs) that were selected for mechanistic studies on myeloma drug resistance: ARP1 and OPM1." (PMID 25230277, 2014).
myeloma (continued). "Our recent studies showed that deficiency in Aldh1a1, but not in Aldh1a2 and Aldh1a3, is the characteristic feature of B cell cancers in humans, especially multiple myeloma (MM)." (PMID 24594504, 2014). "Because cell cycle-dependent protein kinases are thought to be a major underlying reason for CIN and drug resistance in cancer, we hypothesized that NEK2 might be involved in the mechanism by which ALDH1A1 promotes therapy resistance in myeloma." (PMID 25230277, 2014). "Following up on our previous work demonstrating that up-regulation of NEK2 leads to therapy resistance and inferior survival in patients with MM, we decided to explore whether NEK2 might be involved in the mechanism by which ALDH1A1 promotes drug resistance in myeloma." (PMID 25230277, 2014). "ALDH1A1, one of several member of the ALDH1 family, can be readily detected in myeloma cells." (PMID 29100463, 2017). "Additionally, we showed that enforced expression of ALDH1A1 in two myeloma cell lines (ARP1, OPM1) led to both increased clono- and tumorigenicity and heightened tolerance to two widely used myeloma drugs (bortezomib, doxorubicin)." (PMID 25230277, 2014). "To assess whether enforced expression of ALDH1A1 in myeloma cells leads to heightened tolerance to myeloma drugs in vitro, we transduced ARP1 and OPM1 cells with a lentivirus-delivered, EF1-alpha promoter-driven full-length cDNA of ALDH1A1." (PMID 25230277, 2014). "Since ALDH1A1 generates two different RAs – the widely known all-trans retinoic acid (ATRA) and the lesser known 9-cis retinoic acid (9CRA) – and our previous work on myeloma pointed to ATRA as an important signaling ligand, this research concentrated initially on ATRA." (PMID 25230277, 2014).
invasive ductal carcinoma (7 papers, 2010 to 2020). "The ALDH1A1 correlated significantly with malignant proliferations based on Ki67 staining (p=0.001), indicating an association of the ALDH1A1 phenotype with malignant proliferation in invasive ductal carcinoma." (PMID 32695508, 2020). "ALDH1 status was significantly correlated with strong Ki67 staining in all patients (P = 0.001), indicating an association of the ALDH1A1 phenotype with malignant proliferation in invasive ductal carcinoma." (PMID 23767668, 2013). "The ALDH1A1 phenotype is an independent predictor of early tumor relapse that is characteristic of invasive ductal carcinoma." (PMID 24485040, 2014). "In the present study, positive ALDH1A1 expression was observed in 63.0% (92 of 146) of human invasive ductal carcinoma tissues (including slight, moderate, and strong staining), and the incidence of moderate or strong staining were 21.4%." (PMID 23767668, 2013). "Immunohistological analysis of serial tumor sections revealed ALDH1A1 positivity in cells from invasive ductal carcinoma tissues, as illustrated by strong cytoplasmic staining." (PMID 23767668, 2013). "Our findings collectively suggest a possible negative association of the ALDH1A1 phenotype with NOTCH1 in invasive ductal carcinoma." (PMID 23767668, 2013). "The ALDH1A1 phenotype is an independent predictor of early tumor relapse characteristic (specifically, incidence of early local recurrence and distant metastasis) of invasive ductal carcinoma." (PMID 23767668, 2013). "Notably, multivariate Cox proportional hazards regression analysis implied that elevated ALDH1A1 expression in invasive ductal carcinoma is an independent predictor of recurrence-free survival and also distant metastasis-free survival." (PMID 23767668, 2013). "Therefore, the ALDH1A1 phenotype is an independent predictor of early tumor relapse characteristic (specifically, incidence of local recurrence and distant metastasis) of invasive ductal carcinoma." (PMID 23767668, 2013). "The NOTCH1 signaling pathway is possibly involved in the negative association of the ALDH1A1 phenotype with early malignant relapse in invasive ductal carcinoma." (PMID 23767668, 2013).
pancreatic adenocarcinoma (7 papers, 2011 to 2023). "Suppressing Smad4 through specific RNAi upregulates ALDH1A1 mRNA expression whereas Smad4 overexpression downregulates ALDH1A1 mRNA expression in pancreatic adenocarcinoma cells." (PMID 30733805, 2019). "In this study, we investigated the significant role of ALDH1A1 in the chemoresistance of human pancreatic adenocarcinoma to GEM." (PMID 22710732, 2012).
prostate tumor (7 papers, 2017 to 2023). "Treatment of prostate tumor bearing mice with ALK1Fc affected the number of ALDH1A1 positive cells in the prostate tumor tissues both at the protein and mRNA levels." (PMID 29259971, 2017). "Our study identifies PTOV1, ALDH1A1 and CCNG2 as potential markers of metastasis and bad prognosis when detected in primary prostate tumors." (PMID 28938627, 2017). "In this set of tumors, the expression of ALDH1A1 and CCNG2 significantly correlates with prostate tumor aggressiveness, in agreement with previous reports." (PMID 28938627, 2017). "Analyses of tumor datasets show that PTOV1 expression significantly correlated with prostate tumor grade, drug resistance (CCNG2) and self-renewal (ALDH1A1, MYC) markers." (PMID 28938627, 2017). "The expression of ALDH1A1, CCNG2 and MYC genes has been reported in aggressive prostate tumors." (PMID 28938627, 2017).
colorectal tumor (6 papers, 2008 to 2021). "ALDH1A1 protein levels were determined by immunohistochemistry in a series of primary colorectal tumors and their corresponding liver metastases (n = 158)." (PMID 30308036, 2018). "Preferential ALDH1A1 gene expression in CoCSC and sensitization of colorectal tumor cells to 4-HC by inhibiting ALDH1, together strongly suggest that ALDH1 enzyme activity mediates CPA resistance." (PMID 18560594, 2008).
endometriosis (6 papers, 2018 to 2024). The growth of functional endometrial tissue in anatomic sites outside the uterine body. "ALDH1A1 encodes an enzyme that converts retinal into retinoic acid; this pathway has been implicated in endometriosis." (PMID 36304708, 2020). "In order to explore other stromal cell phenotypes useful for more accurately diagnosing endometriosis, we examined ALDH1A1 gene expression comparing cells from endometriosis patients with cells from healthy controls." (PMID 36304708, 2020). "While ALDH1A1 mRNA expression is significantly reduced in endometriosis ME-SFCs, PDPN surface expression is significantly enhanced in endometriosis ME-SFCs." (PMID 36304708, 2020). "We have confirmed in a larger cohort (n = 34 controls and n = 30 endometriosis patients) the significant reduction in ALDH1A1 mRNA expression in ME-SFCs from endometriosis patients compared with cells from controls (P = 0.016)." (PMID 36304708, 2020). "In addition, a significant reduction in ALDH1A1 gene expression and increased podoplanin surface expression were also observed in endometriosis ME-SFCs when compared to control ME-SFCs." (PMID 36304708, 2020). "We show that exposure of ME-SFCs from control subjects to TNF replicates the phenotypes we observed in ME-SFCs from endometriosis patients, including reduced decidualization, reduced expression of ALDH1A1, increased expression of PDPN, and enhanced migration capacity." (PMID 36304708, 2020). "The most striking difference between the control and endometriosis SFCs was the high expression of ALDH1A1 (encoding aldehyde dehydrogenase 1 family member A1) in control SFCs, regardless of treatment." (PMID 30134794, 2018). "This study is the first to demonstrate that uNK cells are significantly reduced in ME obtained from endometriosis subjects and that ME-derived SFCs from subjects with endometriosis exhibit significantly impaired decidualization, along with lower expression of ALDH1A1 than controls." (PMID 30134794, 2018). "ALDH1A1, ALDH1A2 and ALDH1A3 molecules were expressed in the epithelium of ovarian endometrioma posing the possibility that ALDH1+ stem cells could play a role in endometriosis pathophysiology." (PMID 36612107, 2022).
nasopharyngeal carcinoma (6 papers, 2014 to 2022). A carcinoma arising from the nasopharyngeal epithelium. "As for the nasopharyngeal carcinoma, ALDH1A1 mainly played a carcinogenic role." (PMID 36484016, 2022). "To investigate the involvement of stem cells in Epstein-Barr virus infection-related nasopharyngeal carcinoma (NPC), we used double immunofluorescence staining to examine several cancer stem/progenitor cell markers (CD44v6, CD24, and ALDH1A1) in NPC tissues and NPC cell lines." (PMID 27647953, 2016). "Decreased levels of ALDH1A1, ALDH1A2, ALDH1A3, and ALDH1L1 expression were observed in 5 pairwise samples of nasopharynx squamous cell carcinoma (the results are not shown)." (PMID 34680942, 2021).
Oral leukoplakia (6 papers, 2017 to 2024). A thickened white patch on the oral mucosa that cannot be rubbed off. "ALDH1A1 is present in all leukoplakia cases and is likely linked with a significant probability of malignant transformation, particularly in the basal and parabasal layers." (PMID 37489188, 2023). "In addition, ALDH1A1 is overexpressed in leukoplakia cases and underexpressed in OSCC cases [​21], serving as a marker for future cancer cells [​24]." (PMID 37489188, 2023). "ALDH1A1 is more prevalent in leukoplakia than in OSCC ​​​​​​." (PMID 37489188, 2023).
pancreatic ductal adenocarcinoma (6 papers, 2011 to 2025). An infiltrating adenocarcinoma that arises from the epithelial cells of the pancreas. "In our study, we have demonstrated that low expression of ALDH1A1 is an independent prognostic marker for shortened disease-free and overall survival in ductal adenocarcinoma of the pancreas." (PMID 21708005, 2011).
soft tissue sarcoma (5 papers, 2013 to 2020). A malignant neoplasm arising from muscle tissue, adipose tissue, blood vessels, fibrous tissue, or other supportive tissues excluding the bones. "In agreement with the downregulation of ALDH1A1 detected in the xenograft-derived cell lines, low levels of ALDH1A1 expression are strongly correlated (p < 0.0001) with short overall survival among patients with soft-tissue sarcomas." (PMID 31941033, 2020). "We recently found that ALDH1A1 was overexpressed in SFT and HPC as compared to soft tissue sarcomas." (PMID 24252471, 2013). "This is in agreement with our survival analysis on soft-tissue sarcomas demonstrating that upregulated expression of ALDH6A1 but not ALDH1A1 or ALDH3A1 significantly correlates with poor survival when combined with other genes identified in our model, i.e., CDH15, MYOD1, SOX4, ARMCX1, and RYK." (PMID 31941033, 2020).
autism (4 papers, 2019 to 2025). Persistent deficits in social interaction and communication and interaction as well as a markedly restricted repertoire of activity and interest as well as repetitive patterns of behavior. "Our study first found that VPA caused autism-like synaptic and behavioral deficits by impairing the histone acetylation of ALDH1A1 and thus downregulating the RA-RARα pathway, suggesting a precise epigenetic mechanism underlying the VPA-induced autism model." (PMID 33994921, 2021). "In a study of autism rat models, it was found that the retinoic acid synthase ALDH1A1 was downregulated at both mRNA and protein levels in the valproic acid (VPA)-treated offspring." (PMID 40692708, 2025). "This study aimed to investigate the impact of valproic acid (VPA) on the histone acetylation of acetaldehyde dehydrogenase 1A1 (ALDH1A1) and the mechanism underlying VPA-induced autism-like behavior." (PMID 33994921, 2021). "Then, we used the HDAC inhibitor MS-275 to increase AcH3 levels, induce ALDH1A1-RA-RARα signaling and rescue autism-like synaptic and behavioral deficits in VPA-exposed offspring." (PMID 33994921, 2021). "Together, these results clarify that the decreased histone acetylation downregulates ALDH1A1 expression via transcription and impairs the RA-RARα pathway, thereby leading to autism-like synaptic and behavioral deficits in VPA-exposed offspring." (PMID 33994921, 2021). "Such epigenetic modification of ALDH1A1 by VPA leads to autism-like synaptic and behavioral deficits." (PMID 33994921, 2021). "To identify the precise mechanisms of epigenetic modification, we also examined the change in the ALDH1A1-RA-RARα pathway in the PFC of the VPA-induced autism model." (PMID 33994921, 2021). "Therefore, we proposed that VPA-induced histone acetylation disorder leads to autism-like synaptic and behavioral deficits via regulation of ALDH1A1-RA-RARα signaling." (PMID 33994921, 2021). "Although protein–protein interaction data are far from complete, this suggests that Snap25 and Aldh1a1 may be key players in the pathogenesis observed in Fgf14−/− mice and perhaps SZ and/or autism." (PMID 30678040, 2019). "Our study provides novel insights on a SHANK2 mutation derived from autism patient and highlights SHANK2B significance in ALDH1A1 negative DA neuron." (PMID 38704506, 2024).
colorectal adenoma (4 papers, 2015 to 2022). An adenoma that arises from the colon or rectum. "Indeed, we found that ALDH1A1 mRNA levels were significantly higher in normal ‘healthy’ right-sided colon tissue when compared to ‘healthy’ left-sided colon tissue in a cohort of patients diagnosed with colorectal adenomas." (PMID 30308036, 2018).
Hypertension (4 papers, 2021 to 2024). The presence of chronic increased pressure in the systemic arterial system. "ALDH1A1 is identified as a potential therapeutic target treating the comorbidity of hypertension and NAFLD." (PMID 34096467, 2021). "Furthermore, Insig1 expression was low, and Aldh1a1 expression was high in CKD patients with hypertension." (PMID 38806641, 2024). "It seems like inhibiting ALDH1A1 would have some benefits against hypertension-NAFLD complex." (PMID 34096467, 2021).
intrahepatic cholangiocarcinoma (4 papers, 2023 to 2025). A carcinoma that arises from the intrahepatic bile duct epithelium in any site of the intrahepatic biliary tree. "In intrahepatic cholangiocellular carcinoma, ALDH1A1 overexpression correlates with improved survival, highlighting its potential prognostic value." (PMID 40868269, 2025).
liver disease (4 papers, 2014 to 2024). "This link between ALDH1 enzymes and acute response proteins could elucidate the role of Aldh1a1 in liver disease." (PMID 24594504, 2014).